IL2 (interleukin 2)
Diseases named in the same sentence as IL2 in open-access papers (continued):
Sharing a sentence is not in itself a finding about the gene and the disease.
tumor (continued). "Whereas IL-2 enhanced CD8+ T cell proliferation and effector function, IL-21-treated cells exhibited a central memory phenotype, with greater persistence of the cells and higher anti-tumor activityin vivo." (PMID 29123649, 2017). "Step 2 exposure to exogenous IL-7 or IL-7+IL-2 produced selective and sustained expansion of both CD4+ and CD8+ peptide-specific T-cells with a predominant interferon-?-producing T1-type, as well as the antigen-specific ability to lyse tumor targets." (PMID 27974697, 2017). "For example, like IL-2 it enhances CD8+CTL and NK cell proliferation and tumor cell killing." (PMID 29296227, 2017). "Second, transplanting autologous T cells to tumor-bearing NOG mice is not sufficient to achieve tumor eradication unless IL-2 is supplied continuously, which is facilitated by using the hIL2-NOG mice." (PMID 28955032, 2017). "IL-2 was shown to enhance NK and CTL activity against several cancer types; however, this ability is hampered due to the secretion of anti-inflammatory agents, such as TGF-β by tumor cells." (PMID 28220118, 2017). "Further analysis of the IL-2-regulated nuclear phosphoproteome revealed that the ATP-citrate liase ACLY, which is an acetyl-CoA generating enzyme with a relevant role in tumor cell proliferation, was phosphorylated on Ser455 in response to IL-2 stimulation in an Akt-dependent manner." (PMID 28848546, 2017). "Indeed, a recent study demonstrated enhanced anti-tumor effects of NDV engineered to express TRAIL and IL-2." (PMID 27724977, 2016). "Our approach combines these concepts to target a safe form of IL-2 directly to cytotoxic lymphocytes, rather than tumours." (PMID 27650575, 2016). "The decline of IL-2 levels could be due, at least in part, to its consumption by antigen-induced IL-2α receptor+ (CD25+) cells, such as activated tumor-specific CD4- and CD8-T lymphocytes." (PMID 26973649, 2016). "While BRAF-i had no substantial effect, MEK-i sharply reduced tumor cell lysis mediated by IL-2- and IL-15-activated NK cells." (PMID 27563819, 2016). "At day 35, when most of tumors of non-irradiated mice had grown out, there was a statistically significant difference in tumor size between mice that received SBRT and mice that received SBRT + IL-2, SBRT + α-CTLA-4/α-CD137, SBRT + α-PD-1/α-CD137 or SBRT + α-CD137." (PMID 27160390, 2016). "Those TIL cultures that show tumor reactivity by increased secretion of IFN-γ are then expanded with anti-CD3 antibody, IL-2 and allogeneic feeder cells for approximately 14 days, at which time they are then harvested and prepared for infusion into the patient." (PMID 27657129, 2016). "Among the in vivo studies, an ethanol extract from Phoradendron serotinum leaves, tested from 1 to 10 mg/kg i.p., showed immunostimulatory effects, in a dose-dependent manner, by increasing the levels of IFN-γ, IL-2, and IL-6 in serum from C57BL/6 mice bearing TC-1 tumor." (PMID 27042188, 2016). "Moreover, activity tests showed that Se-CEPS improved the immune organ index of CT26 tumor-bearing mice and increased the TNF-α and IL-2 levels in serum." (PMID 27347005, 2016). "The concentration of IL-2 and TNF-alpha are also differently regulated, which may result in enhancing the ability of tumor controlling for cancer patients." (PMID 27015629, 2016). "Additionally, lower intensity TNFR2 expression was observed for tumor-infiltrating CD4+Foxp3− and CD8+ Teff cells, and for PBMC-derived Teff cells following in vitro stimulation with PHA-P/IL-2 or specific cognate antigenic peptide." (PMID 27626702, 2016). "According to several previous studies, interferon (IFN-a) and interleukin-2 (IL-2) do not produce a significant response in this type of tumor." (PMID 27893792, 2016). "Presence of tumor was found to stimulate NK cell expansion in mice treated intraperitoneally with PBMC+Interleukin-2 (IL-2), as compared to no expansion in non-tumor-bearing mice given the same treatment." (PMID 26802025, 2016).
tumor (continued). "Furthermore, αCD40 upregulated IL-2 and the Th1 T cell chemokines, CXCL10 and CXCL11, and increased CD8+ T cell infiltration and tumour PD-L1 expression." (PMID 26918344, 2016). "YPF resulted in the increased expression of IL-2 (p = 0.0498) but significantly downregulated the expression of TGF-β, IDO, and IL-10, suggesting that YPF can result in the downregulation of TGF-β, IDO, and IL-10 in tumor microenvironment." (PMID 27034590, 2016). "To provide more evidence that IL-2 augments the TDLN B cell killer/effector function via the CXCR4/CXCL12 axis, we performed experiments to compare the CXCL12 production by 4T1 tumor cells in the presence or absence of IL-2." (PMID 27528023, 2016). "During cytotoxicity responses, IL2-GMCSF performed multiple roles including improved DC phagocytosis, promotion of cell interactions among DCs, tumor cells and effector T cells, as well as enhancement of T cell activation, which effectively promotes killing efficiency." (PMID 26850448, 2016). "The enhanced immune function, as evidenced by increase of IL-2/-6, and TNF-α, peripheral white blood cells counts, thymus and spleen index following the polysaccharides treatment, might delineate these anti-tumor activities." (PMID 26978396, 2016). "IL-2 or α-PD-1/α-CTLA-4 treatment did not enhance the anti-tumor effect of SBRT (mean TDT of 40.7 (p = 0.71) and 36.8 days (p = 0.60), respectively)." (PMID 27160390, 2016). "Accordingly, the hypothesis of our group is that high concentrations of IL-2 activate immune system cells, such as CD8, CD4 and γδ T cells, and NK cells, to favour the elimination of tumour cells." (PMID 27293315, 2016). "On day 5, TIL were collected, counted and used for in vitro assays TIL from MC-38 tumor expanded two-fold after 5 days of culture in media containing IL-2 (data not shown)." (PMID 27050669, 2016). "In addition to the inherent cytokine activity, IL2-GMCSF bridges direct cell–cell interactions and enhances splenocyte killing efficacy against multiple tumor cell lines in vitro." (PMID 26850448, 2016). "AIT, using IL-2-expanded TIL, resulted in tumor regression in 49% of patients." (PMID 26928306, 2016). "On one hand, IL2-GMCSF can act as an immune enhancer by bringing DCs and other cells in close proximity to enhance the antigen-capturing and presentation efficiency when bound to tumor cells or bound to effector cells, respectively." (PMID 26850448, 2016). "This fusion protein has shown superior anti-tumor activity as compared with ch14.18 mAb combined with IL-2 in NB patients with nonbulky disease." (PMID 27686492, 2016). "Although there was an increased secretion of IL-2 by B7-H3Bi-armed ATC compared with their unarmed ATC counterpart in B7-H3-positive tumor cells, it was not significantly (d)." (PMID 27121051, 2016). "Addition of miR-28 mimics increase the level of IL-2 and TNF-α of T cells, suggesting another benefit of miR-28 that may restore the cytokine secretion function of exhausted T cells in tumor." (PMID 27447564, 2016). "For example, combinatorial treatment of low doses of interleukin-2 (IL-2) and TNF-α in NSCLC patients has resulted in enhanced tumor regression, making these pro-inflammatory cytokines an attractive choice of therapeutic agent to be used in immunotherapy to treat cancer." (PMID 26927069, 2016). "Stimulation of NK cells with IL-2 antibody complexes is very potent for the reduction of tumor burden and viral replication but for retroviral infections complete viral control was not achieved by IL-2 stimulation so far." (PMID 27821119, 2016). "Despite over 20 years of clinical use, IL-2 has not fulfilled expectations as a safe and effective form of tumour immunotherapy." (PMID 27650575, 2016). "IL-2 content was not altered by ZFSC in HT-1080 tumor-bearing mice (p > 0.05), but IFN-γ content was significantly lower in the 1100 mg/kg and 550 mg/kg ZFSC groups compared with the control group (p < 0.05)." (PMID 27493673, 2016).
tumor (continued). "According to our observations, high doses of IL-2 inhibit the proliferation of IL-2R-expressing tumour cells regardless of the cytotoxic function of the activated lymphocytes." (PMID 27293315, 2016). "The lack of significant anti-tumor activity in our patients from IL-2 or anti-CTLA-4 is not surprising in the absence of an effect on GVHD." (PMID 25806109, 2015). "After a single step of magnetic CD3+ T-cell depletion, PBMCs are stimulated and expanded with irradiated autologous cells in the presence of OKT3 and IL-2, resulting in a highly pure population of functional CD3−CD16+CD56+ NK cells that lack cytotoxicity against allogeneic non-tumor cells." (PMID 26029215, 2015). "Gene expression profiling of MCC tumor cells showed the lack of expression of IL-2 and IFN-γ, whereas IL-12 was expressed." (PMID 25866902, 2015). "Untreated or anti-CD16mAb treated NK cells did not secrete IFN-γ when co-cultured with any of the tumor cell populations but did so when treated with IL-2 and with IL-2 in combination with anti-CD16mAb (p < 0.05)." (PMID 26247631, 2015). "Further, IL-2-expressing NK-92 cells where shown to also have enhanced tumor cytotoxicity compared to non-transduced parental NK-92 cells that were stimulated with exogenous IL-2." (PMID 26113846, 2015). "Following the six-day IL-2 driven proliferation with or without 5-aza, we removed IL-2 for two days before subjecting the NK cells to a K562 tumor target cell assay." (PMID 26497557, 2015). "Injection of PEP or IL-2 as positive controls stimulated vasopermeation in the MDA-MB-435 bearing CAMs in a dose-dependent manner with a maximum activity at 0.1 nM, similar to that seen in non-tumor bearing CAMs." (PMID 26510887, 2015). "HPV-positive tumor tissue-derived cell cultures produced markedly higher levels of chemokines, namely CXCL9, CXCL10, CXCL12, CCL17 and CCL21, and slightly higher levels of the cytokines IL-2, IL-17, IL-23 and IFNγ." (PMID 25949860, 2015). "Since a lower concentration of IL-2 induced by tumor PAEP might prevent lymphocytes from proliferation, an adequate exogenous IL-2 was added to each culture conditions." (PMID 25785839, 2015). "The inoculation of EAT stimulated IL-2 release on the 13th day of neoplasm evolution and the treatment with indomethacin did not affect the levels of this cytokine in tumor-bearing animals." (PMID 26347589, 2015). "The IL2 component on these IC has the same ability as soluble IL2 in terms of stimulating cell proliferation via IL2 receptors (IL2R), and have been shown to mediate the conjugation between IL2R-positive cells and tumor target cells." (PMID 26284063, 2015). "A single injection of mice with Hsp70 peptide plus IL-2 activated NK cells, but not with identically stimulated T cells or IL-2 activated NK cells was also able to significantly enhance the OS of tumor-bearing mice." (PMID 25926832, 2015). "Extracellular matrix and tumor cell derived gangliosides (sialic acid glycoproteins), GM2, and GM3 have been demonstrated to diminish NK cell cytotoxicity through contact inhibition to targets, and abrogation of IL-2 dependent proliferation." (PMID 25972872, 2015). "Despite the increase in the IL-2 levels after 13 days of tumor development, the treatment of tumor-bearing mice with indomethacin has not altered the production of this cytokine during the neoplastic growth." (PMID 26347589, 2015). "On the one hand, a membrane (m)Hsp70-positive phenotype correlates with a high aggressiveness of the tumor; on the other hand, mHsp70 serves as a target for natural killer (NK) cells that had been pre-stimulated with Hsp70-peptide TKD plus low-dose interleukin-2 (TKD/IL-2)." (PMID 26579130, 2015). "We also investigated the tumour cell milieu by documenting immunohistochemically the infiltration by CD56+ cells and the presence of in situ cytokines (IL-2, INF-γ and transforming growth factor-beta [TGF-β]) with recognised stimulatory and inhibitory effects in NK cells." (PMID 26040463, 2015).
tumor (continued). "Ten patients who received IL-2 from day 3 through day 8 after an initial Pam infusion (90 mg), however, did not achieve an objective tumor response." (PMID 25686210, 2015). "Treatment of OSCSCs with supernatants from IL-2 + anti-CD16mAb + sAJ2 in the presence of anti-TNF-α had slight enhancing effect on tumor growth, whereas supernatants obtained from anti-IFN-γ in combination with IL-2 + anti-CD16mAb + sAJ2-treated NK cells enhanced tumor cell growth substantially." (PMID 26697005, 2015). "An incubation of purified human NK cells with Hsp70 peptide plus low dose IL-2 resulted in a specific tumor cell killing of mHsp70-positive, but not their mHsp70-negative counterparts, in vitro." (PMID 25926832, 2015). "In other words, tumor cells and lymphocytes are mutually exclusive and never coexist in vitro when cultured in the presence of IL2 for more than 2–3 weeks." (PMID 25262164, 2015). "For example, among cytokines, which are major immune players, IL6 and IL10 are known to cause immune suppression or tolerance, leading to tumor progression, whereas IL2, IL12, IL23, interferon (INF)-alpha and INF-gamma are crucial in immune activation, leading to tumor suppression." (PMID 26674411, 2015). "Functionally, mHsp70 serves as a tumor-specific target structure for cells of the innate immune system, especially Natural Killer (NK) cells that had been activated with Hsp70 peptide TKD plus low dose IL-2." (PMID 26197988, 2015). "Local administration of IL-2 decreased the levels of tumor-infiltrating CD4+ T-cells compared to non-injected control mice." (PMID 26107883, 2015). "Interestingly, UCB-derived CIK cells released higher amounts of IL-2 and IFN-γ and expressed higher levels of CCR6 and CCR7, pointing to a better ability to traffic to tumor sites and secondary lymphoid organs." (PMID 26029215, 2015). "This dichotomy of CD80 expression was found to be critical in the anti-tumor response to systemic IL-12 and peritumoral IL-2 immunotherapy, as tumor generated from cell lines lacking CD80 expression failed to respond." (PMID 26690220, 2015). "As anticipated, the administration of 5 Gy TBI prior to infusion of pmel-1 CD8+ T cells, vaccination, and IL-2 enhanced tumor destruction compared to nonirradiated mice." (PMID 26101781, 2015). "The evidence that cytokines and leukotrienes can increase each other's receptor expression suggests that IL-2, IL-15, and LTB4 may synergize to augment NK cell migration to tumour or infection sites and enhance cytotoxic responses." (PMID 26696753, 2015). "It is noteworthy that the Zol plus IL-2 regimen induces the upregulation of serum vascular endothelial growth factor (VEGF) levels in patients with both solid and hematopoietic tumors, resulting in the promotion of tumor angiogenesis." (PMID 25686210, 2015). "In addition, another interleukin, IL-18, primed “helper” NK cells to produce high levels of the immature dendritic cell (iDC)-attracting chemokines CCL3 and CCL4 upon exposure to tumor cells or the additional inflammatory signals IFN-α, IL-15, IL-12 or IL-2." (PMID 25590298, 2015). "Moreover, fusokines such as the FIST protein, consisting of interleukin-2 (IL-2) and the ectodomain of the TGF-β receptor II, have been developed to combine immune activation and tumor modulation." (PMID 25338019, 2014). "For this purpose, cryopreserved PBMC were thawed and stimulated with a panel of cognate tumor- or viral antigens and their ability to produce key cytokines (i.e. IFN-γ, IL-2 and/or TNF-α) and to express the cytolytic marker perforin were assessed using polychromatic flow cytometry." (PMID 24726012, 2014). "Interestingly, tumor MMP-23 seems to affect specifically TEM cells, as immune biologics including IFN-α, IL-2, and GM-CSF function by targeting TEM expansion." (PMID 25491880, 2014).
tumor (continued). "The higher proliferation of M-406 cells observed when cultured with CMO from both Naïve CBi/L and CBi mice indicates that these media would contain factor/s like IL-2, IL-4, INF-γ, IL-10, TNF-α and many others, yet to be identified, capable to stimulate or inhibit tumor growth." (PMID 24885995, 2014). "We are not implying a direct causal link between hypotension and tumor response, rather that treating patients to their individualized MTD with IL-2 results in durable remissions." (PMID 24855563, 2014). "Moreover, secretion of IL-2 and IFN-γ was even greater when OT-1 T cells were cocultured with IFN-γ-sensitized B16-OVA-USP18 tumor cells as compared with B16-OVA-GFP cells." (PMID 24884733, 2014). "NK cells up-regulated CD69 and CD25 (that associates with CD122 to form the high-affinity receptor for IL-2), expressed CCR7 (a chemokine receptor involved in homing of NK cells to secondary lymphoid organs), increased the anti-tumor cytolytic activity, and released high amounts of IFN-γ." (PMID 24575100, 2014). "Indeed, less IFN-γ and/or IL-2-producing CD4+ T cells were detected, and concomitantly, less efficiency against tumor challenge was found when the booster injections were carried out without AS15 (data not shown)." (PMID 24830315, 2014). "SCP-60 exhibited strong anti-tumor activity in vivo, while SCP-60 at 100 mg/ kg also significantly increased the thymic and spleen indices of S180 mice, and strongly promoted the secretion of IL-2, TNF-α and IFN-γ." (PMID 25068783, 2014). "Almost three decades later, it was observed that the incubation of murine splenocytes with IL-2 generated large numbers of cells, called lymphokine-activated killer (LAK) cells, which were capable of lysing tumor cells with little effect on other somatic cells." (PMID 24860566, 2014). "Our previous research has shown that high mobility group nucleosomal-binding domain 2 (HMGN2) could be released by IL-2 and PHA stimulated peripheral blood mononuclear cells (PBMCs) and also induced tumor cells apoptosis at low doses." (PMID 25060707, 2014). "To determine whether T cells activated with Rv0652-DCs actually exerted tumor-killing effects, we examined exvivo CTL activity and cytokine production, including that of IFN-gamma and IL-2." (PMID 25102137, 2014). "To test whether T cells expressing chA21-28z CAR were capable of specifically recognizing tumor lines expressing HER2, we coincubated CAR T cells with a panel of tumor cell lines and determined the amount of secreted cytokines IFN-γ and IL-2." (PMID 24919843, 2014). "Lymphodepleted, non-tumor bearing mice were adoptively transferred with 5 × 106 Pmel T cells and supported with a dendritic cell vaccine and IL-2 with or without LBH589." (PMID 25054063, 2014). "In contrast to lymphokine-activated killer (LAK) cells, which are cytotoxic effector T-cells stimulated predominantly in response to high concentration of interleukin-2 (IL-2), CIK cells exhibit enhanced tumor cell lytic activity, higher proliferation rate, and relatively lower toxicity." (PMID 24699863, 2014). "The GM-CSF–secreting tumor vaccines conveyed 90% protection, whereas vaccines expressing interleukin-2 and interferon-γ failed to mediate antitumor protection." (PMID 24971166, 2014). "Moreover, the mRNA expression of IL-4 and IL-10 in tumor tissue and pleural effusion of NSCLC patients was significantly higher than that of IL-2, IL-12, and INF-γ." (PMID 24872958, 2014). "In this context, it can be speculated that combined stimulation through IL-2, IL-15 and 4-1BB receptors may enhance Ag-specific CD8+ CTL responses induced by E7 DNA vaccines, thereby conferring more effective tumor control in an HPV E7-expressing tumor model." (PMID 24391824, 2013).